EGFR (epidermal growth factor receptor)
Diseases named in the same sentence as EGFR in open-access papers (continued):
Sharing a sentence is not in itself a finding about the gene and the disease.
pancreatic cancer (continued). "Canertinib and afatinib treated pancreatic cancer cells showed a decrease in phosphorylation of EGFR at tyrosine 1068, HER2 at tyrosine 1248 and HER3 at tyrosine 1289 residues in pancreatic cancer cells at 5 and 1μM concentration respectively." (PMID 25686822, 2015). "To clarify the effects of adding erlotinib to gemcitabine and the roles of EGFR and KRAS mutations as predictive biomarkers in patients with advanced pancreatic cancer who receive these regimens, we performed this open-label, randomized, prospective study." (PMID 26046796, 2015). "Previously, we found that CHIP suppressed pancreatic cancer cell proliferation, anchorage-independent growth, migration and invasion by mediating the degradation of EGFR." (PMID 25635996, 2015). "Recently, preclinical evidence in pancreatic cancer has demonstrated that mutant KRAS can be regulated by EGFR." (PMID 25992771, 2015). "Another important finding in our current study is that these pan-EGFR inhibitors significantly inhibit phosphorylation of AKT at Ser-473 in pancreatic cancer cells." (PMID 25686822, 2015). "To prove this we transiently inhibited endogenous EGFR using siRNA in pancreatic cancer cells and, as expected, transient knockdown of EGFR expression led to inhibition of phospho-STAT1 thereby down regulating MUC4 mucin protein expression." (PMID 25686822, 2015). "In vitro studies of pancreatic cancer reported that a combination of erlotinib and celecoxib downregulated EGFR and COX-2 expression and activation." (PMID 26429877, 2015). "Overall, these results position sugar analogs such as 1,3,4-O-Bu3ManNAc as valuable agents for sensitizing drug-resistant pancreatic cancer to existing therapies that target EGFR." (PMID 25690786, 2015). "In a recent analysis of 2,400 pancreatic cancer patients of whom 82% were found to have mutated KRAS, mutations in BRAF, EGFR, HER2, FLT3, HRAS, PDGFRA, and PTEN were identified exclusively in KRAS wild-type patients, and even there, only rarely (8%)." (PMID 26161408, 2015). "In our previous study, we demonstrated that CHIP is a novel tumor suppressor in pancreatic cancer via the degradation of EGFR." (PMID 25635996, 2015). "We previously found that CHIP served as a novel tumor suppressor by down-regulating EGFR pathway in pancreatic cancer cells." (PMID 25635996, 2015). "This study provides a rationale and strategy for overcoming AZD8055 resistance by a combined treatment with the EGFR inhibitor erlotinib in pancreatic cancer therapy." (PMID 25654224, 2015). "Therapies targeted against EGFR (both TKIs and monoclonal antibody [mAb]) in pancreatic cancer have yielded overall disappointing results so far." (PMID 25935754, 2015). "We observed a significant increase in the inflammatory genes COX-2 and 5-LOX, along with EGFR, in the pancreatic tumors from 44-week-old mice compared with pancreata from wild-type mice, as determined by Next Generation Sequencing/RNAseq analysis." (PMID 26429877, 2015). "First, we aimed to identify the central mechanism through which pan-EGFR inhibitors inhibits MUC4 protein expression in pancreatic cancer cells." (PMID 25686822, 2015). "In ERBB2/EGFR-positive pancreatic cancer cell lines lapatinib has limited efficacy due to k-ras mutations." (PMID 25596742, 2015). "COX-2 and epidermal growth factor receptor (EGFR) were found to be significantly expressed in pancreatic tumors." (PMID 26429877, 2015). "The EGFR-tyrosine kinase inhibitor (EGFR-TKI) erlotinib is the only targeted agent to have demonstrated a small but significant improved survival in advanced pancreatic cancer when combined with gemcitabine." (PMID 25679210, 2015). "As HER family members are involved in pancreatic carcinoma and are activated through dimerization, we tested the combination of cetuximab (anti-EGFR/HER1) and trastuzumab (anti-HER2 antibody)." (PMID 25918250, 2015).
pancreatic cancer (continued). "Once conjugated to a-EGFR, functionalized nanoplates underwent receptor-mediated endocytosis in pancreatic cancer cells that overexpress EGFR, demonstrating their potential for molecular specificity in vitro." (PMID 25530615, 2014). "ATC were harvested and armed with anti-CD3 x anti-EGFR BiAb (EGFRBi) or anti-CD3 x anti-CD20 BiAb (CD20Bi) to test for redirected cytotoxicity against COLO356/FG pancreatic cancer cell line or Burkitt’s lymphoma cell line (Daudi)." (PMID 25008236, 2014). "Small-molecule inhibitors (erlotinib, gefitinib, and afatinib) and a monoclonal antibody (cetuximab) targeted to EGFR have been used for treatment of lung, colorectal, head and neck, and pancreatic cancers." (PMID 24662938, 2014). "Several growth factor receptors such as insulin–like growth factor 1 receptor (IGF-1R), epidermal growth factor receptor (EGFR), etc., are aberrantly expressed in many types of cancer including pancreatic cancer." (PMID 24809702, 2014). "Elotinib is an oral EGFR tyrosine kinase inhibitor that can inhibit the growth and metastasis of human pancreatic tumor xenografts." (PMID 24722501, 2014). "We have recently demonstrated the interest of targeting EGFR/HER2 heterodimers in HER2low- expressing pancreatic cancer." (PMID 25216528, 2014). "Here we show that CHIP interacts and ubiquitinates epidermal growth factor receptor (EGFR) for proteasome-mediated degradation in pancreatic cancer cells, thereby inhibiting the activation of EGFR downstream pathways." (PMID 24722501, 2014). "EGFR over-expression is thought to confer a poor survival, correlating with a more advanced stage and the presence of metastases in pancreatic cancer." (PMID 24722501, 2014). "In conclusion, our study demonstrated that CHIP serves as a novel EGFR-mediated E3 ligase and attenuates the downstream EGFR signaling pathways in pancreatic cancer cells." (PMID 24722501, 2014). "Recently, the CD133 molecule has been linked to tumor malignancy and invasiveness, and overexpression of EGFR and its ligands significantly contributes to the malignant phenotype and correlates with decreased survival in pancreatic cancer patients." (PMID 24625091, 2014). "This drug is widely used in the treatment of advanced non-small cell lung cancer (NSCLC) and pancreatic cancer, primarily to disrupt the EGFR signaling pathway." (PMID 24527088, 2014). "The significant, but modest, increase in median survival obtained with the erlotinib/gemcitabine combination illustrates the potential and the challenges of anti-EGFR therapies in pancreatic cancer." (PMID 25216528, 2014). "Like many chemotherapeutic agents, the effectiveness of EGFR inhibitors have been approved by Food and Drug Administration for use in several tumor cases, alone and in combination with gemcitabine for pancreatic cancer." (PMID 24625091, 2014). "ATC were harvested and armed with CD20Bi or EGFRBi to target CD20 positive Burkitt’s lymphoma cell line (Daudi) or EGFR positive pancreatic cancer cell line (COLO356/FG), respectively." (PMID 25008236, 2014). "Overexpression of EGFR and its persistent activation has been reported to contribute to tumor aggressiveness and chemoresistance in pancreatic cancer." (PMID 24722501, 2014). "Many more recent studies have shown that TGFβ1 and EGFR inhibitors are promising for the treatment of pancreatic cancer." (PMID 24625091, 2014). "Reduced expression of KLF10, as reported for breast and pancreatic cancer, can promote invasive and metastatic behaviour by enhancing EGFR expression." (PMID 24429391, 2014). "Recently, it has been found to promote growth in pancreatic cancer by stimulating the epidermal growth factor receptor." (PMID 24865347, 2014).
pancreatic cancer (continued). "SMI and MoAb of epidermal growth factor receptor (EGFR) such as gefitinib, erlotinib, cetuximab, panitumumab, are widely used for the treatment of lung, colon, and pancreatic cancers." (PMID 24252729, 2013). "Blocking EGFR signaling decreases growth and metastasis of pancreatic tumor in animal models and enhances the effects of gemcitabine." (PMID 23509731, 2013). "While inhibition of Src or EGFR signaling pathways temporarily reduces constitutive STAT3 in pancreatic cancer cell lines, reactivation of STAT3 occurs rapidly." (PMID 24015205, 2013). "In supporting of these findings, activation of the EGFR pathway has previously been reported to be the only reliable predictive factor of erlotinib responsiveness in pancreatic cancer patients." (PMID 23935914, 2013). "Epidermal growth factor receptor (EGFR) is known to be overexpressed in a wide range of cancers, including ovarian, brain, breast, colorectal, kidney, and pancreatic cancers." (PMID 24053278, 2013). "miR-146a can target EGFR, based on predicted base pairing by using miRBase analysis, which has been functionally confirmed in breast cancer and pancreatic cancer." (PMID 23555954, 2013). "Rational targets for this combined approach in pancreatic cancer are EGFR and mTOR, leading to synergistic anticancer activity as has been demonstrated in pre-clinical models." (PMID 22367239, 2013). "Elevated expression of EGFR has been found to be an independent poor prognostic factor in patients with pancreatic cancer." (PMID 23675407, 2013). "Gemcitabine is the standard first line of therapy for pancreatic cancer but has limited efficacy due to inherent or rapid development of resistance and combining EGFR inhibitors with this regimen results in only a modest clinical benefit." (PMID 24025152, 2013). "EGFR is a transmembrane glycoprotein receptor, overexpressed in 90% of pancreatic tumors, which induces tumor cell proliferation and neovascularization; also this expression is associated with worse prognosis." (PMID 23509731, 2013). "EGFR plays an important role in pancreatic cancer cellular proliferation, metastatic spread, and apoptosis." (PMID 23675407, 2013). "In both pancreatic cancer and gastric cancer cells, EGFR and the NF-κB regulatory kinase interleukin 1 receptor-associated kinase 1 (IRAK-1) were proven to be.miR-146a target genes." (PMID 23555954, 2013). "Subsequently, we identified the relative expression of Mig6 and EGFR as a marker of de novo responsiveness to erlotinib in a panel of cancer cell lines, and a unique collection of early passage human lung and pancreas tumors xenografts." (PMID 23935914, 2013). "Other authors reported that the EGFR-integrin interaction seen in pancreatic cancer also increased the migration of colon cancer cells through the integrins α3β1 and α6β4, and acted in hepatocellular carcinoma through integrins α1β1 and α2β1." (PMID 23705994, 2013). "Another, in various cancer types well established, cause of resistance to anti-EGFR treatment is KRAS mutation, predominantly present in pancreatic cancer cells, which accounts for constitutive signaling directly downstream of EGFR." (PMID 22367239, 2013). "Our group previously reported the effective targeting of EGFR-overexpressing pancreatic cancer cells both in vitro and in vivo with gold nanoparticles conjugated with C225 as a targeting agent." (PMID 23483913, 2013). "Studies in human pancreatic carcinoma cells have revealed that 5-FU induces EGFR and Akt phosphorylation." (PMID 24351824, 2013). "It was reported that the combination of gemcitabine with an EGFR-targeting drug was effective against pancreatic carcinoma." (PMID 24649271, 2013).
pancreatic cancer (continued). "Epidermal growth factor receptor (EGFR) tyrosine kinase inhibitors (TKIs) have shown clinical efficacy in lung, colon, and pancreatic cancers." (PMID 22788954, 2012). "In our initial study, we examined the expression levels of EGFR as well as HER-2 on whole cell lysates from four human pancreatic cancer cell lines under basal conditions." (PMID 22134789, 2012). "The majority of pancreatic cancers overexpress EGFR, and this has been correlated with advanced disease at presentation and reduced median survival time." (PMID 22479394, 2012). "It has also been shown that the epidermal growth factor receptor (EGFR) pathway is activated in pancreatic cancer cells by beta-adrenergic, PKA-dependent transactivation of the EGFR." (PMID 22916251, 2012). "In the present study, we investigated the effects of the survivin inhibitor YM155 on survivin, XIAP, and EGFR expression in pancreatic cancer cell lines." (PMID 22723871, 2012). "The members of EGFR have been reported to be often overexpressed in pancreatic cancer cells, which accordantly activated its downstream signaling pathways, such as Ras and ERK, to promote cell growth and survival." (PMID 22848379, 2012). "EGFR is expressed in 30–89% of pancreatic cancers and its aberrant expression has been shown to correlate, in some cases, with worse outcome and more aggressive disease." (PMID 22134789, 2012). "Treatment of pancreatic cancer cells with AS104 leads to significant transcriptional down-regulation of EGFR and HER-2 genes." (PMID 22134789, 2012). "There is a clinical trial (NCT01222689) combining selumetinib and erlotinib (an EGFR inhibitor) in pancreatic cancer patients who have failed gemcitabine therapy." (PMID 23085539, 2012). "To mimic the clinical PD phenomenon and examine the effect of combination therapy of docetaxel with erlotinib, we established an in vivo erlotinib-resistant model using EGFR-positive pancreatic cancer cell line HPAC." (PMID 22209766, 2012). "The phenomenon that targeted therapy containing regimens are ineffective in pancreatic cancer while the same regimens have shown significant activity in other GI tumour entities is also known for anti-EGFR and anti-VEGF drugs." (PMID 22374460, 2012). "In conclusion, we found that YM155, known as a survivin inhibitor, promotes downregulation of PI3K, p-ERK, and p-STAT3 through degradation of EGFR in pancreatic cancer cells." (PMID 22723871, 2012). "Re-expression of miR-146a in pancreatic cancer cells led to the inhibition of both EGFR and NF-kB signaling; this effect is paralleled by a reduced invasion capacity of these cancer cells." (PMID 22453030, 2012). "We previously reported that UVC induced downregulation of the EGFR, which leads to cell growth inhibition in pancreatic cancer cells." (PMID 22200892, 2012). "EGFR-targeted therapeutics, such as erlotinib, have been developed for the treatment of pancreatic cancer." (PMID 22723871, 2012). "More than half of the pancreatic tumors express EGFR, a receptor tyrosine kinase that is responsible for activation of RAS." (PMID 24213498, 2012). "Abnormal signaling in EGFR-related pathways leads to uncontrolled cell growth and has been reported in many solid tumors such as breast, colorectal and head and neck and pancreatic cancers." (PMID 21603581, 2011). "In the present study, we investigated the role of ROCK in the activation of the EGFR and subsequent cell proliferation pathway in pancreatic cancer cells." (PMID 21722395, 2011). "EGFR signaling blockade via a dominant negative mechanism leads to reduction in mitogenic activity in pancreatic cancer cells through decreased activation of MAPK pathway." (PMID 22053213, 2011). "This combination therapy first provided proof of principle of targeting HER1/EGFR in pancreatic cancer and showed erlotinib-improved survival when used concurrently with gemcitabine." (PMID 21922022, 2011).
pancreatic cancer (continued). "Taken together, our findings suggest that ROCK negatively regulates the EGFR pathway in pancreatic cancer cells." (PMID 21722395, 2011). "Our prior findings indicate that pancreatic cancer cells sensitive to EGFR-targeted therapy can be rendered resistant via siRNA-induced ErbB3 inhibition, which suggests a critical influence of ErbB3 in pancreatic cancer EGFR signalling." (PMID 21792199, 2011). "The addition of EGFR-targeted therapy to gemcitabine in advanced pancreatic cancer has recently been demonstrated to provide a small, but statistically significant, survival benefit." (PMID 21722395, 2011). "Epidermal growth factor receptor signalling seems to have an important role in pancreatic cancer tumour progression and EGFR, at least in theory, has been deemed an attractive molecular target for pancreatic cancer treatment." (PMID 21792199, 2011). "Compared with the normal pancreas, EGFR protein and mRNA are expressed at high levels in pancreatic cancer." (PMID 22053213, 2011). "Another study evaluating EGFR as a target in pancreatic cancer, using the monoclonal antibody cetuximab, has been completed." (PMID 21922022, 2011). "TNF-α was found to support pancreatic cancer cell growth through epidermal growth factor receptor (EGFR) and transforming growth factor (TGF-α) expression." (PMID 21880146, 2011). "EGFR is overexpressed in a number of human malignancies including pancreatic cancer, rendering it an attractive target." (PMID 21738572, 2011). "In these studies we employed three different pancreatic cancer cell lines with variable expression of EGFR." (PMID 21738572, 2011). "Re-expression of miR146a inhibited the invasive capacity of pancreatic cancer cells with downregulation of EGFR (epidermal growth factor receptor) and IRAK-1." (PMID 22091404, 2011). "Multimodality treatment incorporating EGFR-inhibition is emerging as a novel strategy in the treatment of pancreatic cancer." (PMID 24212772, 2011). "Though EGFR is abundantly expressed in pancreatic cancer and would thus provide a usable drug target, approaches to inhibit tumor growth have failed so far in clinical trials." (PMID 24212612, 2011). "In the present study, we investigated the role of ROCK in EGF receptor (EGFR) signaling in the pancreatic cancer cell lines, Panc1, KP3 and AsPc1." (PMID 21722395, 2011). "Given the emerging importance of EGFR expression in pancreatic cancer, this report provides an overview of current knowledge in this area with emphasis on the molecular biology of EGFR." (PMID 24212772, 2011). "Our current results confirm that pancreatic cancer cell expression of ErbB3 and ErbB3-mediated signalling modulates response to EGFR inhibition." (PMID 21792199, 2011). "We have also convincingly demonstrated that ErbB3 is the preferential heterodimerisation partner of EGFR in pancreatic cancer cells." (PMID 21792199, 2011). "Expression of EGFR was reported in approximately 70% and production of NT and expression of NTRs in up to 90% of pancreatic tumors and derived cell lines." (PMID 24212612, 2011). "EFEMP1 contains repeated EGF modules and was shown to activate AKT signaling via binding to EGFR in pancreatic carcinoma cells." (PMID 21955618, 2011). "Based on these findings on the molecular alterations of the pancreatic cancers, many therapeutic drugs have been developed by targeting K-ras, EGFR and PI3K/Akt signaling components." (PMID 20423485, 2010). "Inhibition of EGFR by its oral tyrosine kinase inhibitor, erlotinib, has also been shown to have a therapeutic effect on pancreatic cancer." (PMID 20630061, 2010). "Targeting the epidermal growth factor receptor pathway in pancreatic cancer seems to be an attractive therapeutic approach." (PMID 19293797, 2009). "Concomitant expression of epidermal growth factor receptor (EGFR) with its ligand, such as EGF, transforming growth factor α (TGFα) or amphiregulin has been associated with decreased patient survival in pancreatic cancer." (PMID 16822304, 2006).